IL6 (interleukin 6)
Diseases named in the same sentence as IL6 in open-access papers (continued):
Sharing a sentence is not in itself a finding about the gene and the disease.
glaucoma (continued). "We then examined the gene expression of several proinflammatory cytokines (TNFα, IL-1β, IL-6, and IL-18) and chemokines (MIP-1α, MIP-1β, MIP-2, MCPI, and IP10) that have been implicated in human and experimental models of glaucoma." (PMID 31570110, 2019). "Further, although increases in TNFa, and IL6 have been shown to contribute to glaucoma pathogenesis, we do not detect increases in either in our model, in fact, TNFa was below the detection limit in our assay." (PMID 31354422, 2019). "For example, one previous study found that serum interleukin (IL)-4 and IL-6 cytokines produced by T helper cell 2 were elevated in glaucoma patients; these cytokines also activate B cells to produce IgE." (PMID 29285264, 2017). "IL-6 mRNA and protein are upregulated near retinal ganglion cells (RGCs) and their axons in rodent models of glaucoma." (PMID 28620279, 2017). "While our findings support a role for IL-6 in the progression RGC degeneration in glaucoma, we utilized IL-6-/- mice that are generated from homozygous pairing." (PMID 28620279, 2017). "Not surprisingly in this context, the presence of inflammatory markers, such as IL-6, IL-8, and the vascular endothelial leukocyte-adhesion molecule (ELAM)-1, in the aqueous humor have been linked with the pathogenesis of glaucoma." (PMID 28797085, 2017). "Clusterin functions as a chaperone and was described to be neuroprotective in the context of glaucoma in the interplay between interleukin-6 (IL-6), vascular endothelial growth factor (VEGF), and hypoxia-1α." (PMID 29135941, 2017). "To examine the impact of IL-6 deficiency on the progression of IOP-induced RGC neurodegeneration, we utilized the microbead occlusion model of glaucoma to elevate IOP for a total of 8 weeks in WT and IL-6-/- mice." (PMID 28620279, 2017). "The pleotropic cytokine interleukin-6 (IL-6) is implicated in retinal ganglion cell (RGC) survival and degeneration, including that associated with glaucoma." (PMID 28620279, 2017). "Our previous work identified IL-6 signaling through gp130 as a relevant inflammatory pathway in glaucoma, a neurodegenerative disease affecting RGCs." (PMID 27747134, 2016). "The number of glaucoma medications was positively correlated with G-CSF (ρ = 0.464; P = 0.004), IL-6 (ρ = 0.443; P = 0.007), and IL-8 (ρ = 0.439; P = 0.007)." (PMID 26748993, 2016). "In this context, we examined the same neuroinflammatory, cell health and gp130 regulatory factors in IL-6−/− and WT mice 4 weeks after induction of microbead-induced glaucoma." (PMID 27747134, 2016). "RGC neurodegeneration, microglia reactivity and IL-6 signaling in glaucoma occur in a spatially-dependent manner." (PMID 25133067, 2014). "We also observed comparable trends for pro-inflammatory regulations in glaucomatous retinal tissues in our study like elevated concentrations of TNF-α (p = 0.13), IL-1β (p = 0.08), IL-6 (p = 0.26) and IL-8 (p = 0.04) compared to non-glaucoma controls." (PMID 23451242, 2013). "Our study also showed a significantly higher proportion of glaucoma aqueous with a measurable concentration of IL-6 cytokine." (PMID 22355254, 2012). "IL-6 is an important immune mediator in the prediction model of primary open-angle glaucoma." (PMID 40486511, 2025). "Furthermore, previous studies correlated increased IL-6 in the AH of patients with diabetic retinopathy or primary open-angle glaucoma to smoking." (PMID 40075380, 2025). "In addition, the IL-6/IL-10 ratio seems to perform better than IL-6 alone as a predictor of the severity of primary open-angle glaucoma." (PMID 39765793, 2024). "Notably, the aqueous humor of patients with glaucoma has higher concentrations of cytokines, such as IL-4, IL-6, IL-8, IL-10, vascular endothelial growth factor, and interferon-α, compared to healthy individuals." (PMID 38651060, 2024).
glaucoma (continued). "However, more recently, in a microbead-induced glaucoma murine model, it was shown that IL-6 plays a key role in the process of structural degeneration of the optic nerve and that its absence prevents not only this latter, but also vision loss." (PMID 38337691, 2024). "Furthermore, increased preoperative levels of IL6 in the aqueous humour are correlated with poor glaucoma surgery outcome." (PMID 38990974, 2024). "Additionally, IL-6 was higher in the ‘POH group’ compared to the ‘glaucoma group’ (p = .04) and IL-4 was higher in the ‘POH group’ compared to the ‘normal group’ (p = .04)." (PMID 35998207, 2022). "It was found that Ba alleviates the expression of pro-inflammatory cytokines including TNF-α, IL-6, and IL-1β in mouse microglia, supporting its biomedical significance for glaucoma treatment as elevated levels of TNF-α, IL-6, and IL-1β are observed in the TM of glaucoma patients." (PMID 35806375, 2022). "Previous studies also suggest that during glaucoma macrophages produce cytokines such as IL6, IL1β and TNFα that could lead to an acute inflammatory response." (PMID 35619185, 2022). "While IL1B and IL6 may be associated with the risk of glaucoma, GPX and TNF may affect the glaucoma phenotype." (PMID 33803434, 2021). "In conclusion, genetic variability in IL1B and IL6 may be associated with glaucoma risk, while GPX and TNF may be associated with the glaucoma phenotype." (PMID 33803434, 2021). "The anti-inflammatory properties of iTRAB® were investigated in 3D-HTMCs through its ability to modulate the increase in pro-inflammatory (i.e., IL-1α, IL-1β, IL-6, and TNF-α) and pro-fibrotic cytokines, as well as MMPs which are known to be associated with glaucoma." (PMID 33172106, 2020). "Many studies of different types glaucoma have shown an increased level of IL-6 in aqueous humor." (PMID 32117217, 2020). "Another group found the levels of IL-8, TGFβ-1, TNF-α, and SAA to be significantly increased in POAG and pseudoexfoliation glaucoma (PEXG) patients compared with controls, while levels of IL-6 were significantly decreased in both glaucoma groups compared with controls." (PMID 29675026, 2018). "IL-1β expression was also reduced specifically in IL-6−/− retina with microbead-induced glaucoma." (PMID 27747134, 2016). "The number of glaucoma medications was positively correlated with G-CSF, IL-6, and IL-8." (PMID 26748993, 2016). "Overall, our findings support a role for IL-6 in setting baseline parameters for neuroinflammatory, cell health and gp130 regulatory signaling that can impact the nature and magnitude of retinal responses to glaucoma-related stressors." (PMID 27747134, 2016). "Our findings support a role for IL-6 in setting baseline parameters for neuroinflammatory, cell health and gp130 regulatory signaling that can impact the nature and magnitude of retinal responses to glaucoma-related stressors." (PMID 27747134, 2016). "Several earlier studies also demonstrated that the anti-glaucoma medications changed the expression levels of matrix metalloproteinases (MMPs) and tissue inhibitors of metalloproteinases (TIMPs), as well as the synthesis of interleukin (IL)-6 in Tenon’s fibroblasts cultured from glaucoma patients." (PMID 26017119, 2015). "An increased protein level was measureable for TNF-α (TNF-α: ctrl = 538±200 U, glaucoma = 907±454 U; p = 0.13) and the interleukins IL-1ß (IL-1β: ctrl = 11262±2590 U, glaucoma = 15625±4194 U; p = 0.08) and IL-6 (IL-6: ctrl = 8301±2287 U, glaucoma = 12073±6695 U; p = 0.26)." (PMID 23451242, 2013). "Based on the reported literature, the aim of the present study was to investigate the Hep and IL6 levels in the aqueous humor and serum of patients with primary open-angle glaucoma (POAG) and compare these with senile cataract patients as a comparative (control) group." (PMID 21031015, 2010).
glaucoma (continued). "It is known that the inflammatory pathological milieu consequent to both glaucoma surgery wound and topical long-term glaucoma treatment further induces conjunctival fibroblasts to secrete various growth factors and proinflammatory cytokines, such as IL-1β and IL-6." (PMID 38391973, 2024). "However, this mouse model has never been used to study the retina, despite IL-6 being associated with retinal inflammation, diabetic retinopathy, and glaucoma." (PMID 38983084, 2023). "In this 24-month prospective longitudinal observational cohort, 57 participants (19 controls, 19 prostaglandin-treated glaucoma, 19 untreated glaucoma) underwent spectral-domain OCT, validated sleep assessment, and serial IL-6 and TNF-α profiling." (PMID 41683759, 2026). "Inflammatory cytokines, such as TNF-α, IL-1β and IL-6, have been identified to clearly contribute to RGC death in glaucoma." (PMID 40528237, 2025). "IL-6, the primary activator of the JAK/STAT signaling pathway, has been detected in the aqueous humor of glaucoma patients." (PMID 39555089, 2024). "Most likely other inflammatory cytokines are involved as well, especially IL-6 and IL-1β, but the role of TNF-α in glaucoma has been under strong suspicion for over two decades." (PMID 37803488, 2024). "For instance, several inflammatory cytokines and chemokines, i.e., IL-6, TNF, CXCL12, and CXCL8, showed elevated centrality values in various networks, evidencing the detrimental role of neuroinflammation in glaucoma." (PMID 39458974, 2024). "In primary open-angle glaucoma (POAG), serum IL-6/IL-10 ratio contributed to discriminate the disease progression." (PMID 36371539, 2022). "IL-4 and IL-6 levels were higher in the ‘POH group’ compared to the ‘normal group‘ and ‘glaucoma group’, respectively." (PMID 35998207, 2022). "), TNFα, interleukin-6 (IL-6), and FasL) which contribute to RGC damage and apoptotic cell death in glaucoma." (PMID 38983517, 2022). "In studies focusing on prostaglandin analogue-treated glaucoma patients, IL1B, IL6, and matrix metallopeptidases 1, 3, and 9 (MMP1, MMP3, and MMP9) were seen to be increased, while TIMP metallopeptidase inhibitors 1 and 2 (TIMP1 and TIMP2) were decreased." (PMID 35897711, 2022). "In summary, our study showed that the expression levels of TNF-α, IL-2, IL-6, IL-8, BDNF, MMP-2, MCP-1, VEGF, IFN-γ, LT-α, bFGF, PDGF-AA, and TIMP-1 were different among the 3 types of glaucoma." (PMID 36254076, 2022). "The levels of TNF-α, MMP-2, MCP-1, IFN-γ, TIMP-1, IL-6, IL-8, VEGF, and LT-α were different among the three types of glaucoma." (PMID 36254076, 2022). "An increase in inflammatory cytokines IFN-γ, IL-6, IL-4, IL-10, and IL-1β resulted in a reduction of brn3a+ RGC cells in a glaucoma mouse model, and is thought to be related to microglial activation." (PMID 34439904, 2021). "In primary open angle glaucoma (POAG) eyes, the level of IL-12, IL-6, TNF-α, IL-8, IFN-γ were noted to be remarkably raised." (PMID 32117217, 2020). "Many of the cytokines with increased expression measurements in our study (IL-1α, IL-1β, IL-6, TNF-α, FasL) were already described as being elevated in glaucoma patients." (PMID 30967499, 2019). "To determine whether IL-6-mediated changes in gp130 signaling impact the inflammatory, cell survival and gp130-related regulatory response of the retina to glaucomatous stressors, we examined gene expression of Tnfα, lL-1β,Bcl-xl, Bax and Socs3 in the Microbead Occlusion Model of murine glaucoma." (PMID 27747134, 2016). "In the iris of glaucoma patients, expression of Th1 cytokines (IL-2 and IFN-γ) increased, Th2 cytokine IL-6 decreased, and TGF-β increased." (PMID 25811482, 2015).
glaucoma (continued). "Our previous clinical study showed significantly lower serum TNF-α in primary open-angle glaucoma (POAG) patients than in controls, while the levels of IL-4, IL-6, and IL-12p70 were significantly higher." (PMID 25811482, 2015). "This study was designed to evaluate the levels of Interleukin-6 (IL6) and Hepcidin prohormone (Hep) in the serum and aqueous humor of patients with primary open-angle glaucoma (POAG), as well as those with senile cataract as a control group." (PMID 21031015, 2010). "However, in prolonged glaucoma pathology, uncontrolled microglial activation leads to the release of neurotoxic pro-inflammatory cytokines, including TNF-α, IL-6, and IL-1β, exacerbating neurodegeneration." (PMID 40457155, 2025). "In addition, IL-6, a primary activator of the JAK/STAT signaling pathway, was detected in the aqueous humor of glaucoma patients." (PMID 39555089, 2024). "Moreover, ELISA analysis showed the level of IL-6, IFN-β, and CXCL10 were also elevated in glaucoma as compared to the sham group, suggesting an inflammatory response in glaucoma." (PMID 38848144, 2024). "Importantly, the continuous secretion of SASP such as MCP1, TNF-α, CSF and IL6 accelerated the death of RGC, leading to the aggravation of glaucoma." (PMID 37525172, 2023). "Significantly higher serum levels of IL-4, IL-6, and IL-12 (p70), along with lower TNF-α, were determined in POAG patients compared to controls, suggesting abnormal immune environments contributing to glaucoma." (PMID 34439995, 2021). "In the DBA2J mice, an experimental glaucoma model that developed PAS at 50 weeks, the AqH levels of IL-2, IL-6, IL-10, IFN-γ, tumor necrosis factor-α, MCP-1 and granulocyte-macrophage colony-stimulating factor (GM-CSF) significantly increased at 50 weeks compared to 8 weeks (p ≤ 0.021)." (PMID 34830147, 2021). "Additionally, a glaucoma animal model, DBA2J, developed PAS and iris atrophy with age, and the AqH levels of IL-1β, IL-6, IL-10, IFN-γ, TNF-α, MCP-1 and GM-CSF at 50 weeks were significantly higher than those at 8 weeks." (PMID 34830147, 2021). "Furthermore, a statistically significant increased IL-6 concentration was significantly detected in the aqueous humor and plasma samples of POAG patients respect to the CG, reinforcing the role of INF in glaucoma neurodegeneration." (PMID 32967086, 2020). "Early elevation of pro-inflammatory cytokines (specific factors not identified) is speculated to involve TNF-α, IL-1, and IL-6, influencing the neuroinflammatory process in glaucoma." (PMID 40486511, 2025). "Therefore, reducing the secreted IL-8 and IL-6 levels can at least partly explain the benefit of ripasudil in the treatment of HTLV-1-infected hTM cells, further supporting the feasibility of using ripasudil for the relief of secondary glaucoma in HU." (PMID 38542203, 2024). "Additionally, DLG4 (discs large MAGUK scaffold protein 4) and several proinflammatory chemokines and cytokines already known to have a role in glaucoma, e.g., C-X-C motif chemokine ligand 8 (CXCL8), tumor necrosis factor (TNF), and interleukin-6 (IL-6), were other central nodes in the network." (PMID 39458974, 2024). "Ten’s research showed that the expression of IL-2, IL-6, monocyte chemoattractant protein-1 (MCP-1), and placental growth factor (PlGF) were significantly up-regulated in the intraocular fluid of RP patients, and the level of IL-8 was higher in presence of glaucoma." (PMID 34399712, 2021). "Indeed, as a consequence of glaucoma-related harmful stimuli (including optic nerve injury, IOP elevation, and excitotoxicity), reactive glial cells redistribute throughout the retina and the optic nerve, where they start producing inflammation mediators such as IL-6 and TNF-α." (PMID 38337691, 2024).
glaucoma (continued). "Proinflammatory mediators such as TGFβ, IL-6, and IL-8 are reported to be involved in the pathogenesis of XFG36–40, and our present result suggested that ATX may also be an important factor, which stimulates the inflammatory and fibrotic phase after glaucoma filtration surgery." (PMID 30054520, 2018). "To further understand the consequences of the ketogenic diet on inflammation, we examined the expression of pro-inflammatory cytokine IL-6 and NOS2 in D2 glaucoma mice with or without the ketogenic diet." (PMID 30424795, 2018). "In conclusion, reduction in IL-6 would help in reducing the effects of glaucoma as with the other inflammatory cytokines of CXCR4, IL-17, IL-1β, and TNF-α which are known to be increased in PC-12-glaucoma model cells without betalain treatment." (PMID 32666339, 2020).